TRIB2 (tribbles pseudokinase 2)
Diseases named in the same sentence as TRIB2 in open-access papers (continued):
Sharing a sentence is not in itself a finding about the gene and the disease.
tumor (continued). "Nevertheless, Gilby and colleagues found that TRIB2 can act as tumour suppressor in AML and accordingly its expression was downregulated in patient samples." (PMID 34070799, 2021). "PDX tumor #07, which has high TRIB2 expression, and PDX tumor #12, which has low TRIB2 expression, were used in these experiments." (PMID 34586732, 2021). "miR-509-5p as a tumor suppressor can target Trib2 and suppress cell propagation and migration in OS cell lines." (PMID 33794905, 2021). "The tumor growth curve further demonstrated that the downregulation of TRIB2 and RFWD2 inhibited tumor formation." (PMID 34646775, 2021). "The authors included an initial GEO database analysis, and found that TRIB2 was highly expressed in primary tumor tissues compared with adjacent normal tissues." (PMID 34198908, 2021). "Consistent with our findings, miR-511 acts as a tumor suppressor gene that attenuates tumor cell growth and proliferation by inhibiting tribbles pseudokinase 2 (TRIB2)." (PMID 32554864, 2020). "In general, TRIB2 overexpression increased the expression of genes that promote tumor progression, while it repressed those genes known to prevent tumor progression." (PMID 33316942, 2020). "a Tumor volumes of TRIB2-overexpressed or TRIB2-overexpressed plus AP4 knockdown or control groups were calculated every 4 days." (PMID 30541550, 2018). "The present study expands our understanding of TRIB2 in cellular senescence, and suggests that TRIB2/AP4/p21 pathway is a potential target for tumor therapeutic intervention." (PMID 30541550, 2018). "Tribbles homolog 2 (TRIB2) pseudokinase functions as both an oncogene and a tumour suppressor with important roles in human health and disease." (PMID 29599919, 2018). "In contrast, TRIB2 has tumour suppressor activities in acute leukaemia, linked with aberrant MAPK signalling that resulted in tumour cell death." (PMID 29599919, 2018). "In contrast, studies have revealed tumour suppressor functions of Trib2, including pro-apoptotic and reduced MAPK signalling." (PMID 29599919, 2018). "Consistent with the result, tumor size and weight of TRIB2 overexpressed group were larger than that of the vector group and TRIB2 plus shAP4 group." (PMID 30541550, 2018). "In this study, we investigated one underlying molecular mechanism between unregulated TRIB2 and Cisplatin-resistance in both the Cisplatin-resistant SCLC cell model and in pilot studies of human SCLC tumor specimens." (PMID 29312632, 2017). "We verified that the Cisplatin-treated tumor cells were indeed much more resistant to Cisplatin in vitro and determined that the TRIB2 gene expression levels increased significantly." (PMID 29312632, 2017). "Analysis of more tumor samples will be needed to definitively establish/verify a relationship between natural platinum resistance and TRIB2 and CEBPA protein expression." (PMID 29312632, 2017). "It was subsequently confirmed in an independent study that this tumor-suppressor activity of TRIB2 is lymphoid cell specific." (PMID 27908682, 2017). "Phosphorylated ERK was not detectable in either group and no change in AKT phosphorylation was observed between Trib2-/- and Trib2+/+ tumor cells expressing ICN1." (PMID 27191957, 2016). "Our finding that absence of Trib2 promoted Notch-induced T-ALL was surprising as TRIB2 expression correlates with activated NOTCH1 in primary patient tumor samples." (PMID 27191957, 2016). "Despite a substantial increase in protein levels, the C/EBPα target genes Mpo, Ltf, and Lyz2 remained undetectable in sorted tumor cells from Trib2+/+ and Trib2-/- mice, and expression of the myeloid marker Itgam did not change (data not shown)." (PMID 27191957, 2016). "This appears to be consistent with the role of TRIB2 in other solid and hematological malignancies that overexpression of TRIB2 confers growth and survival advantages to tumor cells." (PMID 27462446, 2016).
tumor (continued). "In addition, both TCF3 and TRIB2 were significantly overexpressed in HB compared with non-tumor tissues across two independent cohorts (GSE132219 and GSE104766)." (PMID 41462308, 2025). "This indicates that the PI3K and MAPK pathways are not likely to mediate the tumor-suppressive effects of TRIB2 in GC, which is therefore associated to additional downstream effectors." (PMID 38254916, 2023). "Our results suggest a tumor-suppressive function of TRIB2 in GC with a CIN phenotype." (PMID 38254916, 2023). "We also found that TRIB2 siRNA decreased LNCaP-ENR tumor growth in nude mice." (PMID 34973338, 2022). "In other tumor types, however, different mechanisms for TRIB2 regulation have been described." (PMID 34198908, 2021). "Nevertheless TRIB2 has been shown to act both as an oncogenic driver and tumour suppressor in AML." (PMID 34070799, 2021). "Though ACVR2A mutations, reported in several cases of CRC, have been previously linked to earlier tumor stages (stages I/II), TRIB2 correlation to tumor staging was not performed within this study." (PMID 34198908, 2021). "Furthermore, several recent articles suggest the implication of TRIB2 in the tumour sensitivity to cisplatin." (PMID 34070799, 2021). "In addition, the overexpression of TRIB2 in tumor tissues induces drug resistance by promoting phospho-AKT (at Ser473) via its COP1 domain." (PMID 34646775, 2021). "Besides, TUG1 depletion inhibited tumor growth and the level of TRIB2 was clearly declined, but the expression of miR-542-3p was markedly increased." (PMID 34030715, 2021). "The expression of TRIB2 in tumor tissues and cell lines is significantly increased." (PMID 33794905, 2021). "It is important to note that the cause of TRIB2 overexpression in neoplasias has not been elucidated, although we know that TRIB2 is strictly regulated at both the transcriptional level and protein level." (PMID 34070799, 2021). "Interfering with TRIB2 activity might be a therapeutic strategy for the treatment of diverse tumor types and, particularly, to overcome therapy resistance." (PMID 33316942, 2020). "CRC samples from patients with tumor recurrence expressed higher TRIB2 levels." (PMID 30541550, 2018). "TRIB1 and TRIB2 have potent oncogenic activities in vertebrate cells, and recent evidence also suggests that TRIB2 acts as a tumour suppressor, consistent with the requirement for balanced TRIB signaling in the regulation of transcription, differentiation, proliferation, and apoptosis." (PMID 27908682, 2017). "Our analysis suggests that TRIB2 possesses tumor-suppressive functions important for T-ALL." (PMID 27462446, 2016). "Decrease in MEIS1, GFI1 and cMYC, has been shown to inhibit tumour cell growth, and an increase in TRIB2 may be pro-apoptotic." (PMID 24708856, 2014). "We also showed that inhibition of TRIB2 expression by its relevant miRNA (miR-511 or miR-1297) could induce tumor cell apoptosis." (PMID 23071539, 2012). "Moreover, TRIB2 overexpression implies tumour resistance to PI3K/mTOR inhibitors, so it might also be useful as a predictive biomarker in a personalized therapy context." (PMID 34070799, 2021). "Thus, TRIB2 emerges as a novel regulator of thymocyte cellular proliferation, important for the thymopoietic response to genotoxic and oncogenic stress, and possessing tumor suppressor function." (PMID 27462446, 2016). "Additionally, dual-luciferase reporter transfection assay and western blot analysis indicated that miR-99a may target CTDSPL and TRIB2, which are two tumor suppressor genes." (PMID 24191888, 2013). "On the other hand, TRIB2 may serve as a tumor suppressor gene." (PMID 24191888, 2013). "​In conclusion, we delineate a coherent oncogenic framework in which SE-driven TRIB2 expression is activated by TCF3, leading to NRF2 stabilization that suppresses ferroptosis and promotes tumor proliferation in HB." (PMID 41462308, 2025).
tumor (continued). "Data mining of the TCGA dataset revealed that chromosomal instability (CIN) tumors have lower TRIB2 and higher TRIB3 expression versus microsatellite instability (MSI)-high tumors, while TRIB1 levels are similar in both tumor types." (PMID 38254916, 2023). "ThereforeTUG1 is regarded as a tumor promoter that stimulated CRC pathogenesis and drug resistance through the miR-542-3p/TRIB2 axis." (PMID 36333703, 2022). "The authors demonstrated TRIB2 negatively regulated p21 at the promoter level, through TRIB2 kinase-like domain binding and cooperation with AP4, which was elevated in CRC tumor compared with the corresponding normal tissues." (PMID 34198908, 2021). "In lung cancer, Trib2 binds with TRIM21 E3 ligase and decreases expression levels of C/EBPα, which accelerates cell proliferation and tumor growth." (PMID 33794905, 2021). "Thus, downregulation of TUG1 could suppress tumor growth by miR-542-3p/TRIB2 axis in vivo." (PMID 34030715, 2021). "The weight and growth curve of the xenografts showed that TRIB2 overexpression promoted tumor formation, whereas RFWD2 knockdown inhibited tumor formation and reduced tumorigenesis in xenografts stably expressing TRIB2." (PMID 34646775, 2021). "TUG1 served as a tumor promoter, impeded the progression of CRC by miR-542-3p/TRIB2 axis to inactivate of Wnt/β-catenin pathway, which providing a novel target for CRC treatment." (PMID 34030715, 2021). "Similar patterns were also observed in limited human tumor specimens of chemo-resistant SCLC patients: namely, overexpressed TRIB2 and undetected CEBPA proteins." (PMID 29312632, 2017). "In view of the challenge in obtaining SCLC tumor tissue before therapy and upon progression to compare their expression of TRIB2, we have started to develop similar SCLC in vivo models of Cisplatin-resistance using patient-derived SCLC tumor samples." (PMID 29312632, 2017). "Given the relatively high expression of Trib2 in developing T cells and its positive correlation with human T-ALL, we were surprised to find that Trib2 functioned as a tumor suppressor in our murine Notch1-induced T-ALL model." (PMID 27191957, 2016). "However, the mechanisms that underlie whether TRIB2 acts as an oncogene or tumor suppressor are not well understood." (PMID 27462446, 2016). "In this respect, treatment with MRS1220 reduced the transcripts of 29 genes that could tentatively favor the tumor phenotype; three targets that promote chemoresistance, LIMD1, TRIB2, and TGFB1, were distinguished." (PMID 38794149, 2024). "This suggests that TRIB2 might play a tumor-suppressive role in GCs with a CIN phenotype, its downregulation being advantageous for tumor progression." (PMID 38254916, 2023). "Note: To confirm the specificity of TRIB2 antibodies, we used a panel of TRIB2-negative and TRIB2-positive cell lines and tumor tissues and analyzed by both Western blot as well as immunohistochemistry." (PMID 34973338, 2022). "It is particularly noteworthy that a PDX model using human clinical ESCC specimens substantiates our in vitro results showing that TRIB2 strongly induced radioresistance, while HDAC2 inhibition effectively blocked the effects of TRIB2 and strengthened the suppression of tumor growth by radiotherapy." (PMID 34586732, 2021). "To determine the role of TRIB2 in CRC, we firstly analyzed the publically available human CRC datasets from Gene Expression Omnibus (GEO) databases, and found that TRIB2 was highly expressed in primary tumor tissues compared with adjacent normal tissues." (PMID 30541550, 2018). "b and c Tumor size and weight of tumors generated from TRIB2-overexpressed SW48 cells transfected with or without AP4-specific siRNA and control cells." (PMID 30541550, 2018).
tumor (continued). "The overexpression of Trib2 in AML does not result in total C/EBPα degradation in the tumor cells; instead, there appears to be preferential degradation of the p42 C/EBPα isoform that results in a relative increase in expression of the p30 C/EBPα isoform." (PMID 27191957, 2016). "However, we did not observe activation of these two signaling molecules, indicating that TRIB2 does not exert its tumor suppressor function in CIN GC cells through this specific pathway." (PMID 38254916, 2023). "Therefore, since the putative role of TRIB2 in GC is unknown, we focused our attention on TRIB2 by investigating whether TRIB2 expression in CIN and MSI tumors correlates with clinicopathological parameters such as sex, tumor stage, and histological grade." (PMID 38254916, 2023). "In contrast, the low TRIB2‐expressing PDX tumor was not sensitive to SCA treatment following IR." (PMID 34586732, 2021). "Moreover, the CSC properties were significantly reduced, whereas p21 expression was greatly enhanced in TRIB2‐high but not in TRIB2‐low tumor xenografts following SCA treatment." (PMID 34586732, 2021). "Thus, patients whose tumours display high TRIB2 expression may not benefit from specific PI3K inhibitor therapeutics, rendering TRIB2 as a suitable biomarker predicting treatment outcome and selecting patients for individualized therapy." (PMID 34070799, 2021). "In contrast, Stein and colleagues found that knockdown of TRIB2 in murine T-ALL cell lines did not affect cell growth or survival and rather acts as tumour suppressor in Notch-driven T-ALL." (PMID 34070799, 2021). "Moreover, this inhibition is specific for TRIB2 because of the lack of equivalent Cys residues in other pseudokinases, including TRIB1, TRIB3, and STK40, indicating the convenience of this therapeutic approach for tumours in which high levels of TRIB2 correlates with worst prognosis." (PMID 34070799, 2021).
adenocarcinoma (3 papers, 2012 to 2022). A common cancer characterized by the presence of malignant glandular cells. "Both the Beltran and Labrecque databases show overexpression of TRIB2 in NE-type prostate cancers compared to adenocarcinoma." (PMID 34973338, 2022). "We predicted the possible miRNAs targeting the 3′-UTR of TRIB2 using microRNA analysis software and tested their effects on human adenocarcinoma cell apoptosis." (PMID 23071539, 2012). "Our results demonstrated that the apoptotic rate was increased in the miR-511 (or miR-1297)-treated cells compared with the negative-control miRNA (NC)-treated cells, and these miRNAs could reduce adenocarcinoma cell proliferation by inhibiting TRIB2 expression." (PMID 23071539, 2012).
hematological malignancies (2 papers, 2019 to 2023). "Growing evidence suggests the role of TRIB2 as a pro-oncogene with a regulatory function underlying drug resistance both in solid and hematological malignancies." (PMID 31337155, 2019).
TRIB2 also shares sentences with these, for which no sentence is quoted: T-cell acute lymphoblastic leukemia (6 papers); Autoimmunity (2); laryngeal squamous cell carcinoma (2); acute pancreatitis (1); alcoholism (1); Alzheimer disease (1); bacterial infection (1); benign prostatic hyperplasia (1); bladder cancer (1); Cataplexy (1); coinfection (1); epilepsy (1); graft versus host disease (1); hepatoblastoma (1); Hypertension (1); idiopathic hypersomnia (1); Insulin resistance (1); kidney damage (1); lipoma (1); liver fibrosis (1); lung squamous cell carcinoma (1); neuroblastoma (1); neurological disease (1); Opioid dependence (1); papilloma (1); serous ovarian cancer (1); small cell lung carcinoma (1); viral infection (1).